MTND4P35 (MT-ND4 pseudogene 35)
Gene: Processed pseudogene on chromosome 5 (100,048,988 to 100,050,362, reverse strand). Ensembl gene ENSG00000270906.
Diseases named in the same sentence as MTND4P35 in open-access papers:
MTND4P35 is named in the same sentence as 1 disease in open-access papers, as found by Europe PMC text mining. Sharing a sentence is not in itself a finding about the gene and the disease.
MTND4P35 shares sentences with these, for which no sentence is quoted: skin cutaneous melanoma (1 paper).